Y_RNA (Y RNA )
Gene: Miscellaneous RNA gene on chromosome 1 (91,261,625 to 91,261,724, forward strand). Ensembl gene ENSG00000206817.
Homologues: Orthologues: chimpanzee Y_RNA (99% identical), macaque Y_RNA (95% identical), guinea pig Y_RNA (91% identical), macaque Y_RNA (91% identical). Paralogues in human: Y_RNA (89% identical), Y_RNA (88% identical), RNY3 (87% identical), Y_RNA (87% identical), Y_RNA (86% identical), Y_RNA (85% identical), RNY3P1 (84% identical), RNY3P14 (84% identical), Y_RNA (84% identical), Y_RNA (83% identical), RNY3P11 (82% identical), RNY3P13 (82% identical), and 94 more.